HMGA2 (high mobility group AT-hook 2)
Diseases named in the same sentence as HMGA2 in open-access papers (continued):
Sharing a sentence is not in itself a finding about the gene and the disease.
adenocarcinoma (11 papers, 2012 to 2025). A common cancer characterized by the presence of malignant glandular cells. "HMGA1 and HMGA2 evaluation in esophageal carcinoma revealed interesting differences between adenocarcinoma and squamous histotypes." (PMID 25859543, 2015). "Genetic alterations in the pleomorphic adenoma gene 1 (PLAG1) and the high-mobility group AT-hook 2 (HMGA2) genes are frequently seen in both PAs and Ca ex PAs, although these alterations are not typical of primary SDC, MECA, or adenocarcinoma NOS." (PMID 40002255, 2025).
connective tissue tumors (4 papers, 2014 to 2017). "This pattern is similar to the rearrangements of HMGA2 found in other benign connective tissue tumors, i.e., disruption of the HMGA2 locus leaves intact exons 1-3 which encode the AT-hook domains and separates them from the 3 ́-terminal part of the gene." (PMID 28591699, 2017). "This pattern is similar to the rearrangements of HMGA2 found in other connective tissue tumor types, i.e., disruption of the HMGA2 locus leaves intact exons 1–3 which encode the AT-hook domains and separates them from the 3′-terminal part of the gene." (PMID 26043835, 2015). "The present case of myolipoma underscores the frequent and general role of HMGA2 rearrangements in the genesis of several benign connective tissue tumors." (PMID 26857357, 2016). "The cytogenetic change leads to expression of HMGA2 or formation of HMGA2 chimeras, i.e., the same pathogenetic motifs that are well known also from other benign connective tissue tumors." (PMID 26043835, 2015). "The CSF1-S100A10 fusion gene is reminiscent of the HMGA2-fusions in benign connective tissue tumors." (PMID 24604026, 2014).
infection (4 papers, 2011 to 2024). The state of being infected such as from the introduction of a foreign agent such as serum, vaccine, antigenic substance or organism. "We observed that WT- and NPC-iNSCs showed no detectable expression of retroviral specific SOX2 and HMGA2, whereas WT- and NPC-hDFs on day 5 after infection exhibited high expression levels, suggesting that exogenous factors were silenced in both WT- and NPC-iNSCs." (PMID 29156730, 2017).
colon (3 papers, 2019 to 2021). "HMGA2 is mainly overexpressed in gastrointestinal tumors, including in CRC." (PMID 33536018, 2021). "Additionally, it has also been reported that HMGA1 and HMGA2 possess an important biomarker potential for the detection and progression of gastrointestinal (GI) tumors." (PMID 31737655, 2019). "Additionally, it has also been reported that HMGA1 and HMGA2 display an important role in the detection and progression of GI tumors." (PMID 31737655, 2019).
cardiovascular diseases (1 paper, 2024). "Blocking HMGB1’s inflammatory signaling pathways holds promise as a novel therapeutic strategy for cardiovascular diseases, while modulating HMGA2 expression has the potential to delay disease progression by improving myocardial remodeling and repair processes." (PMID 39507236, 2024). "Therefore, regulating HMG proteins, particularly HMGB1 and HMGA2, could have a significant impact on the treatment of cardiovascular diseases." (PMID 39507236, 2024).
intestinal diseases (1 paper, 2024). "Relevant proteins such as CALU, FLNA, MSN and HMGA2, which are related to intestinal diseases, were all upregulated in the IBD duodenal organoids." (PMID 38203746, 2024).
HMGA2 also shares sentences with these, for which no sentence is quoted: asthma (3 papers); benign mesenchymal tumors (3); chondroma (3); pulmonary hamartomas (3); seminoma (3); ampullary adenocarcinoma (2); anaplastic thyroid carcinomas (2); atypical lipomatous tumor (2); biliary atresia (2); breast fibroadenoma (2); deafness (2); Diabetic Nephropathy (2); endometrioid adenocarcinoma (2); hematological diseases (2); lung (2); lymphoma (2); multiple myeloma (2); Osteochondroma (2); papillary carcinoma (2); papillary renal cell carcinoma (2); prostate adenocarcinoma (2); smooth muscle tumor (2); squamous cell carcinoma of the vulva (2); teratoma (2); yolk sac tumor (2); achondroplasia (1); acute erythroleukemia (1); acute promyelocytic leukemia (1); adenoid cystic carcinoma (1); adrenocortical adenomas (1).
A further 106 diseases each share a sentence with HMGA2 in 1 paper.